OPA1 (OPA1 mitochondrial dynamin like GTPase)
Diseases named in the same sentence as OPA1 in open-access papers (continued):
Sharing a sentence is not in itself a finding about the gene and the disease.
optic atrophy (continued). "This patient had a complex phenotype, with sensory ataxia and axonal neuropathy compatible with FRDA, but in addition a severe optic atrophy, making the clinical picture more consistent with a severe OPA1 phenotype." (PMID 26338206, 2015). "Mutations in OPA1 are the most common cause of isolated optic atrophy with dominant inheritance (ADOA), as well as “plus” phenotypes where optic atrophy is accompanied by syndromic features, such as neurosensory deafness and ophthalmoplegia." (PMID 26251896, 2015). "OPA8: One large family with a optic atrophy undistinguishable from that related to OPA1 was recently described." (PMID 22776096, 2012). "Patients with Leber hereditary optic neuropathy, another spontaneous optic neuropathy with a genetic pathophysiology, had decreased OPA1 expression in blood." (PMID 22550394, 2012). "These proteins act together with the optic atrophy protein 1 (OPA1), and an inner mitochondrial membrane (IMM) located dynamin-like GTPase mutated in heritable optical atrophy." (PMID 19421406, 2009). "The detected proteins are involved in a wide range of diseases; spastic paraplegia (HSPD1), cancer (BAX, PHB), optic atrophy (OPA1), ethylmalonic encephalopathy (ETHE1) and Parkinson's disease (NDUFV2)." (PMID 19476632, 2009). "For example, missense mutation in the GTPase domain, such as the dominant-negative variant of OPA1-linked ADOA often results in early-onset, severe optic atrophy, whereas truncating mutations may produce milder or later-onset phenotypes." (PMID 41268195, 2025). "The optic atrophy is conclusively attributed to the OPA1 deletion, and the aneurysm could be a coincidental association." (PMID 38641846, 2024). "In conclusion, the optic atrophy is conclusively attributed to the OPA1 deletion, and the aneurysm could be a coincidental association." (PMID 38641846, 2024). "This might also have affected studies for revealing functions of proteins localizing at IMM, such as the dynamin-related GTPase Optic Atrophy 1 (OPA1), a gene responsible for optic atrophy." (PMID 37651352, 2023). "In total, 116 patients with suspected optic neuropathy were examined, and 25 cases of LHON were diagnosed.The diagnostic rate for LHON of the Part A was 21.6% in our optic atrophy group using the mtDNA Sanger sequencing panel (OPA1, WFS1, etc., not included)." (PMID 33781268, 2021). "Indeed, besides LHON, in most cases the degeneration of RGCs leading to optic atrophy is imputable to OPA1 dysfunctions." (PMID 33806088, 2021). "OPA1 is related with optic atrophy and optic atrophy plus syndrome." (PMID 34440452, 2021). "OPA1 mutations should not be considered only for dominant trait or only for optic atrophy phenotypes." (PMID 28494813, 2017). "Humans with OPA1 mutations develop optic atrophy typically after age 10 and loss of the RGC layer is not observed until postmortem examination." (PMID 23516612, 2013). "Interestingly, several diseases besides MS show a predominant impairment of these parvocellular axons such as Leber’s hereditary optic neuropathy, OPA1 related dominant optic nerve atrophy, and spinocerebellar ataxia type 1." (PMID 23805202, 2013). "Moreover, variants in nuclear genes OPA1, OPA3, TYMP and POLG have been reported in patients with other optic atrophies with phenotypes that could be similar to LHON." (PMID 36827238, 2023). "Although previous studies reported this variant as disease-causing and non-penetrance was well characterized in OPA1-dominant optic atrophy, this variant might be questionable in pathogenicity." (PMID 36071901, 2022). "In some circumstances, individuals with an OPA1 variant may not develop a clinically relevant optic atrophy." (PMID 34573359, 2021). "In the year 2000, the human OPA1 gene came to attention, as heterozygous mutations were associated with dominant optic atrophy (DOA), a blinding disorder originally described by the Danish ophthalmologist Paul Kjer in 1959, which usually leads to optic atrophy in the first decade of life." (PMID 34177786, 2021).
optic atrophy (continued). "However, OPA1 mutations, responsible for optic atrophy and neurological disorders, seem not to be associated with cancer." (PMID 34674701, 2021). "Moreover, our findings suggest that bi-allelic OPA1 mutations should be considered in disorder where optic atrophy is not obvious (or even absent)." (PMID 28494813, 2017). "OPA4 and OPA5: three families linked to the OPA4 or OPA5 loci present an optic atrophy that can not be differentiated from the phenotype observed in OPA1 patients: i.e. optic nerve pallor, decreased visual acuity, color vision defects, impaired VEP, and normal ERG and no extra-ocular findings." (PMID 22776096, 2012). "The main consequence of the OPA1-related DOA is the degeneration of retinal ganglion cells, the axons of which form the optic nerve, resulting in optic atrophy, which is frequently bilateral and symmetric." (PMID 33578638, 2021). "Even though optic atrophy does occur in FRDA patients it is uncommon, and a primary OPA1 diagnosis is further supported by frataxin level only in the carrier range." (PMID 26338206, 2015). "Hence, optic atrophy is a common feature of mitochondrial disorders, and two other nonsyndromic causes of optic atrophy, LHON and autosomal dominant optic atrophy Kjer type, are caused, respectively, by mutations in mitochondrial DNA and the nuclear gene OPA1 that encodes a mitochondrial protein." (PMID 20405026, 2010). "As cI dysfunction is central to LHON, and prominent cI impairment is also detected in OPA1-related ADOA, it is not surprising that mutations in other cI-related genes may lead to optic atrophy when mutated." (PMID 35008635, 2021). "Clinical features in P3 were particularly misleading for an OPA1 related condition, with manifestations of early onset progressive spastic ataxia and sensory motor polyneuropathy, in the absence of optic atrophy." (PMID 28494813, 2017). "Concerning the two proteases of OPA1, while mutations in OMA1 have not been associated with human disease yet, homozygous mutations in YME1L have been reported in four patients from a consanguineous Saudi Arabian family presenting an infantile-onset mitochondriopathy with optic atrophy." (PMID 33806088, 2021).
Optic neuropathy (48 papers, 2008 to 2026). "Mutations in OPA1 are known to cause Kjer’s dominant optic atrophy, the most common hereditary optic neuropathy." (PMID 41149856, 2025). "Sensorineural hearing impairment was found in 62.5% of OPA1 mutation carriers and was the second most common main clinical characteristic in ADOA-plus patients among the extraocular diseases, other than optic neuropathy brought on by OPA1 gene mutations." (PMID 36980899, 2023). "DOA caused by OPA1 variants is the commonest inherited optic neuropathy in the general population, resulting in progressive blindness in children and young adults." (PMID 37974363, 2023). "The OPA1 mutation caused DOA is the most prevalent inherited form of optic neuropathy, characterized by the gradual degeneration of retinal ganglion cells (RGCs) and the optic nerve." (PMID 36157077, 2022). "The current literature reports 8 patients carrying LHON mtDNA mutations and 2 patients harboring OPA1 mutations who developed optic neuropathy during the use of EMB." (PMID 34676220, 2021). "In this review, OPA1 plays an essential role in modulating mitochondrial fusion by regulating and stabilizing cristae formation, and mutations in human OPA1 are associated with dominant optic neuropathy." (PMID 34201955, 2021). "Of these patients, seven had a family history of optic neuropathy, two carrying an OPA1 mutation and four harboring an mtDNA mutation." (PMID 34676220, 2021). "Optic atrophy 1 (OPA1) gene mutations are associated with dominantly inherited optic neuropathy resulting in a progressive loss of visual acuity." (PMID 32883255, 2020). "The dysfunction of mitochondria caused by mutations in the OPA1 gene in ADOA is thought to be associated with apoptosis of retinal ganglion cells leading to optic neuropathy." (PMID 22879959, 2012). "All genes involved in hereditary optic neuropathies known to date are mitochondrial (LHON) or nuclear genes encoding proteins with mitochondrial targeting (OPA1, OPA3)." (PMID 22815638, 2012). "Nevertheless, OPA1 is known to affect mitochondrial stability and has now been implicated in several spontaneous optic neuropathies." (PMID 21552501, 2011). "The presence of an OPA1 mutation indicates that this sporadic, late-onset acute case of optic neuropathy is related to ADOA and to a mitochondrial energetic defect." (PMID 19325939, 2009). "Some classically “isolated” optic neuropathy genes have more pleiotropic effects in certain contexts—for instance, about 20% of patients with OPA1 mutations develop extra-ocular neurological features (hearing loss, myopathy, peripheral neuropathy), a phenotype known as “DOA+”." (PMID 40332750, 2025). "Notably OPA1 variants can cause inherited optic neuropathy, which occurs isolated or along a broader phenotype with sensory ataxia, sensorineural deafness and myopathy, resembling the full-blown phenotype of advanced FRDA." (PMID 38027498, 2023). "A recent study has drawn attention to the underdiagnosis of optic neuropathy due to OPA1 mutations." (PMID 34679672, 2021). "It has been implicated in the pathogenesis of several other spontaneous optic neuropathies, and this study suggests that OPA1 expression may also play a role in the development of POAG." (PMID 21552501, 2011). "In addition to optic neuropathy, more than 20% of patients with OPA1 mutations manifest neurodegenerative problems such as ptosis, ataxia, peripheral neuropathy, mitochondrial myopathy, and progressive external opthalmoplegia as well as bilateral sensorineural hearing loss." (PMID 36980899, 2023). "The authors then combined their data with 193 reported Han Chinese patients with optic neuropathy and compared these to the available data of 4327 East Asians by the Exome Aggregation Consortium (ExAC) and found a significant enrichment of potentially pathogenic OPA1 mutations." (PMID 34679672, 2021). "Both OPA1 and WFS also cause optic neuropathy, in the form of Kjer’s dominant OA and Wolfram syndrome, respectively." (PMID 41149856, 2025).
Optic neuropathy (continued). "Optic neuropathy or dominant optic atrophy (DOA) is a dominant and inherited mitochondrial disease majorly caused due to mutations in OPA1." (PMID 38012514, 2024). "Mutations of the OPA1 gene are responsible for 50–70% of ADOA, which is the most common form of inherited optic neuropathy." (PMID 34676220, 2021). "The possibility to transfer idebenone therapy from LHON to OPA1‐related DOA would represent a very relevant option to fight blindness in the largest categories of inherited optic neuropathies." (PMID 32243103, 2020). "The dysfunction of OPA1, a dynamin GTPase involved in mitochondrial fusion, is responsible for a large spectrum of neurological disorders, each of which includes optic neuropathy." (PMID 31500643, 2019). "It should be stressed that there is no report of such a foveal lesion in the most frequent OPA1 forms, nor in all the optic neuropathies related to other genetic causes." (PMID 34548540, 2021). "In 2013, we reported a pilot study on seven patients with another inherited optic neuropathy due to mitochondrial dysfunction, dominant optic atrophy (DOA) associated with OPA1 haploinsufficiency heterozygous mutations, who were treated for at least 1 year with idebenone." (PMID 32243103, 2020). "Although unusual, some patients with genetically-confirmed OPA1 mutations have been described with acute and even reversible visual loss, and a subgroup of LHON patients can present with a slowly progressive optic neuropathy, more suggestive of DOA." (PMID 21112411, 2011). "OPA1 abnormalities are now recognized in several spontaneous optic neuropathies." (PMID 21552501, 2011). "This variant is localized in the ATPase domain of the AFG3L2 clustered in the ATPase domain with other pathogenetic variants causing alteration of OPA1 processing and associated with optic neuropathy, presenting clinical features nearly indistinguishable from OPA1-related DOA." (PMID 39564550, 2024). "However, an amplitude reduction of VEP response was found for 15’ stimuli: abnormalities in VEP 15’ responses, which mainly reflect macular fibers responses contributing to the temporal quadrant of the optic nerve, are quite typical of OPA1- related optic neuropathy." (PMID 28494813, 2017). "Dominant optic neuropathy is caused by mutations in the nuclear gene such as OPA1 and the irreversible visual loss often occurs in the childhood although late-onset optic neuropathy after 4th decade and adult-onset CPEO and parkinsonism with subclinical optic neuropathy have recently been described." (PMID 26315846, 2016). "Thus, direct enhancement of OPA1 may provide a new strategy to protect RGC death in various optic neuropathies including glaucoma." (PMID 20664796, 2010). "However, heterozygous eat-3 mutations have no overt defects in worms, unlike heterozygous Opa1 mutations in humans, which cause optic neuropathies through haploinsufficiency." (PMID 18454199, 2008). "In our North of England inherited optic neuropathy cohort, DOA+ phenotypes were observed in 1 in 6 OPA1 carriers, which clearly indicate that these syndromal variants affect a significant patient subgroup." (PMID 21112411, 2011). "If red light therapy is able to inhibit the age-dependent RGC degeneration and visual impairment in Opa1+/− mice, it may have potential as a future treatment for ADOA and other optic neuropathies involving RGC pathology." (PMID 34445085, 2021). "Although the optic neuropathy found in the OPA8 family seems indistinguishable from that described in the OPA1 disease, the hearing dysfunction appears profoundly different." (PMID 31191217, 2019). "Although probably very uncommon, the possible involvement of AFG3L2 and SPG7 in optic neuropathies should prompt the screening of these genes in isolated and syndromic DOA patients, negative for OPA1 and OPA3 mutation." (PMID 26539208, 2015).
Optic neuropathy (continued). "Caporali and co-workers performed an exhaustive study on the role of AAAs in optic neuropathy where their studies showed using both yeast and patient fibroblast that AFG3L2 mutations indirectly affect OPA1 processing, resulting in mitochondrial fragmentation not seen in SCA28 patients." (PMID 38012514, 2024).
heart failure (41 papers, 2010 to 2025). Inability of the heart to pump blood at an adequate rate to meet tissue metabolic requirements. "Cardiomyocyte-specific Yme1L deficient mice exhibit reduced Opa1 levels via activation of Oma1, leading to a shift in cardiac metabolism and, ultimately, heart failure." (PMID 37895224, 2023). "Impaired Opa1 processing has been reported to cause dilated cardiomyopathy and heart failure, indicating an intriguing involvement of CL-regulated Opa1 processing." (PMID 34392401, 2021). "Imbalanced OPA1 processing and mitochondrial fragmentation upon cardiac deletion of Yme1l are associated with cardiomyocyte death and heart failure, which can be suppressed by additional deletion of Oma1." (PMID 30389680, 2019). "Decreased Opa1 levels have been associated with cardiomyopathy and heart failure in mice, whereas enhancing Opa1 levels protected mice hearts and brain from ischemic damage." (PMID 29257072, 2017). "Disruption of mitochondrial dynamics through deletion of OPA1 or imbalanced OPA1 processing also causes mitochondrial fragmentation, bioenergetics deficit and heart failure in mice." (PMID 27818636, 2016). "This hypothesis is supported by the fact that knocking out the fusion proteins OPA1 and Mfn2 caused heart failure." (PMID 39570915, 2024). "Reduced OPA1 promoted apoptosis and mitochondria fragmentation, which may contribute to heart failure progression with progressive loss of cardiac myocytes." (PMID 36776252, 2023). "This imbalanced Opa1 processing was reported to cause heart failure in mice." (PMID 33805825, 2021). "Studies have shown that the occurrence of heart failure may be related to the fragmentation and dysfunction of mitochondria caused by the short-form aggregation of OPA1." (PMID 34660720, 2021). "Research suggests that mitochondrial fission proteins like Drp1 and Mff become more active in cardiac hypertrophy and heart failure, while the fusion protein Opa1 activity diminishes, indicating an imbalance towards excessive fission within cardiomyocytes." (PMID 40078364, 2025). "A separate investigation revealed that in both humans and dogs with heart failure, cardiomyocytes display reduced levels of Mfn2 and Opa1, alongside an increase levels of Drp1 and Fis1." (PMID 40078364, 2025). "Western blotting results showed that the expressions of MFN2 and OPA1 proteins were down-regulated in the heart failure group, and up-regulated by aerobic exercise and SKQ1." (PMID 40076760, 2025). "The OPA1 level decreases in heart failure and conversely, low OPA1 level can manifest in impaired heart function." (PMID 39570915, 2024). "Studies have shown that protein levels of OPA1 were reduced in both rat and human heart failure models accompanied with mitochondrial fragmentation." (PMID 36776252, 2023). "OPA1 is a mitochondrial inner membrane protein that helps regulate the fusion of mitochondria and is downregulated by ischemia and heart failure." (PMID 38052926, 2023). "Expression of OPA1 is decreased in both human and rat heart failure and decreased in mice and cells subjected to hypoxia." (PMID 37212935, 2023). "Opa1 is reduced in rat heart failure models after MI and in tissue samples of human dilated and ischemic cardiomyopathy." (PMID 37895224, 2023). "Other reports suggest that mitochondrial fusion events via OPA1 or MFN1/2 appear to decrease in heart failure, as well." (PMID 34912235, 2021). "The absence of YME1L in cardiomyocytes activates OMA1, which further increases the processing level of OPA1, increases the fragmentation of mitochondria, and ultimately leads to dilated cardiomyopathy and heart failure." (PMID 34660720, 2021). "Levels of OPA1 were also found to be decreased in a post-MI rat heart failure model and human dilated and ischemic cardiomyopathy tissue samples." (PMID 28190190, 2017).